STAT3 (signal transducer and activator of transcription 3)
Diseases named in the same sentence as STAT3 in open-access papers (continued):
Sharing a sentence is not in itself a finding about the gene and the disease.
tumor (continued). "Current studies have confirmed that STAT3-mediated inhibitory tumor immune response has an antagonistic effect on STAT1-driven antitumor immune response, which may lead to the loss of function of the IFNγ/JAK/STAT1 pathway." (PMID 36185620, 2022). "These suggest that CAF in tumor microenvironment promotes the progress of GC through IL-6/JAK2/STAT3 signal transduction, and IL-6 targeted therapy may become a complementary treatment for GC by acting on stromal fibroblasts." (PMID 36591515, 2022). "Various mediators, including transcription factors, such as nuclear factor-kB (NF-kB), signal transducers, such as signal transducer and activator of transcription 3 (STAT3), proinflammatory cytokines, chemokines, and matrix metalloproteinases (MMPs), work together to enhance the tumor environment." (PMID 35892729, 2022). "miR-301 inhibition reduced the activity of NF-κB and Stat3 in both tumor and immune cells." (PMID 35211358, 2022). "To our knowledge, we have, for the first time, reported that HMGA2 bound directly to the -743/-730 and -585/-576 promoter regions of STAT3 and in turn promoted its transcription and expression, thus enhancing tumor immune evasion and facilitating tumor progression in CRC." (PMID 34976223, 2022). "In addition, we demonstrated that the forced overexpression of STAT3 in H146 cells increased the tumor proliferation ability in a mouse xenograft model." (PMID 35885009, 2022). "Interestingly, this phenomenon was also shown in other tumor types, such as STAT3 contradictory roles in non-small lung cancer." (PMID 35327992, 2022). "However, in addition to its functions in the normal cells, STAT3 activation in the tumor microenvironment (TME) is regarded as an oncogenic event." (PMID 35356799, 2022). "Here, we detected a reduced number of Ki67+ EpCAM+ cells in Stat3ΔCol1a2 mice as compared with littermate controls, indicating the reduced proliferation of tumor epithelial cells in mice with conditional STAT3 inactivation in type I collagen-expressing fibroblasts." (PMID 35326623, 2022). "In addition, on the one hand, neutrophils/chemerin activated JAK2/STAT3 pathway and upregulated its down stream cycle-related proteins to promote tumor proliferation." (PMID 35155249, 2022). "Increased IL-6 secretion was ultimately shown to lead to IL-6-mediated Janus activated kinase (JAK) activation in tumor cells with subsequent downstream phosphorylation and activation of the transcription factor signal transducer and activator of transcription 3 (STAT3)." (PMID 35965494, 2022). "All cancer cell lines were statistically equally sensitive to treatment as MDA-MB-231, suggesting that the MC-based STAT3 decoy strategy could be applied not only to TNBC but also to other human tumor types." (PMID 35847174, 2022). "Moreover, STAT3 leads to the transcription of other soluble mediators that reprogram the TME towards a pro-tumor phenotype." (PMID 35406557, 2022). "STAT1 is considered to be a tumor suppressor while STAT3 is rather seen as an oncogene." (PMID 35267462, 2022). "The activation of STAT3 in a tumorigenic region improves cancer cell proliferation and inhibits apoptosis, which may be the reason for in situ tumor recurrence after thermal ablation." (PMID 35053608, 2022). "In addition to these molecules, previous studies confirmed that the Kirsten rat sarcoma viral oncogene homolog (KRAS), transforming growth factor beta (TGF-β), and STAT3 pathways also played a key role in tumor glucose metabolism." (PMID 36124026, 2022). "In addition, radotinib repressed expression of the activity and expression of STAT3, and its downstream proteins including Bcl-xL, Mcl-1, c-Myc, cyclin D1, and cyclin D3 in IM-9 cells isolated from the tumor tissue." (PMID 35503759, 2022). "Furthermore, in nude mice xenografted with Eca109 and CaEs-17 cells, AZD9150, the generation 2.5 antisense oligonucleotide inhibitor of STAT3, was observed to inhibit tumor proliferation and liver and lung metastasis." (PMID 35264069, 2022).
tumor (continued). "PTPRK was reported to inhibit tumor progression by directly targeting STAT3 activation." (PMID 36341348, 2022). "Betulinic acid inhibited the expression of MMP2, MMP9 and p-STAT3 in 4T1 tumor tissues." (PMID 36615262, 2022). "STAT3 is a transcriptional regulator of numerous factors that are involved in tumor progression." (PMID 35281907, 2022). "CM from human umbilical cord MSCs suppressed the activation of STAT3 signaling and tumor growth." (PMID 35741334, 2022). "Importantly, NDV is used to treat different tumor types have different effects when the context of inhibiting STAT3 expression." (PMID 36466838, 2022). "In addition, TNF-alpha, IL-17, and IL-6 have also been shown to induce tumor growth through NF-kappa B and STAT3 activation." (PMID 35563010, 2022). "Stat3 can act both as a potent tumor promoter and a tumor suppressor factor." (PMID 35681623, 2022). "Additionally, CTLA4(apt)-STAT3 siRNA demonstrated a substantial inhibiting impact on tumor development and metastasis in a variety of mouse tumor models." (PMID 35890239, 2022). "In this review, we summarize recent advances in our understanding of the functional role of STAT3 in tumor progression and introduce novel molecular mechanisms of cancer development and malignant transformation involving STAT3 activation that we have identified to date." (PMID 36010693, 2022). "Solamargine initiated the repolarization of M2-like towards M1-like phenotype via decreasing the expression of leukemia inhibitory factor (LIF) derived from tumor cells, an immunosuppressive mediator that activated the STAT3 signaling to alter the differentiation of immune cells." (PMID 36615387, 2022). "STAT3 is considered to be one of the key signals driving tumor development." (PMID 35288541, 2022). "As a transcription factor, STAT3 could promote growth and inhibit apoptosis of tumor cells by mediating transcription of downstream target genes, especially cyclin D1." (PMID 36157053, 2022). "B lymphocyte-derived factors have also been shown to upregulate proteins and transcription factors involved in pro-inflammatory signaling pathways such as IKK complex proteins and STAT3 in tumor cells, resulting in tumor-promoting processes such as inflammation and angiogenesis." (PMID 35255925, 2022). "Additionally, tocilizumab has already been used in some cancer models with important effects in different tumor cell models, mainly on the proliferation, invasion, and sensitization to drugs through dephosphorylation of STAT-3." (PMID 35465350, 2022). "We further assessed the role of PPARγ in suppressing tumor growth through modulation of STAT3." (PMID 36362294, 2022). "Chloroquine could substantiate the anti-tumor effects of pterostilbene on PC through the inhibition of autophagy via downregulating RAGE/STAT3 and protein kinase B (AKT)/mammalian target of rapamycin (mTOR) signaling pathway." (PMID 36408249, 2022). "Thus, NCT-80 appeared to inhibit STAT3/Wnt signaling-mediated signaling in vivo in the PDX tumors, causing apoptosis and thereby suppressing tumor growth." (PMID 34987637, 2022). "In addition, studies have also revealed that over-activated Stat3 in tumor cells can inhibit the maturation of dendritic cells and innate immunity, thereby reducing the anti-tumor effector function of CD8+T cells." (PMID 36454780, 2022). "In view of our findings, there may be homology between this human Breg population and mouse tumour-infiltrating, STAT3-dependent B cells identified in such studies." (PMID 35660734, 2022). "In tumor cells, over-activated STAT3 decreases the expression of immunostimulatory factors, including pro-inflammatory cytokines (IL-12, TNF-α), IFN and chemokines (CCL5, CXCL10), while increasing the expression of certain cytokines (IL-6, TGF-β, and VEGF), thus playing an immunosuppressive effect." (PMID 36313280, 2022).
tumor (continued). "In addition to pro-angiogenic mediators, STAT3 also upregulates cyclin D1 and Bcl-2, resulting in rapid tumor growth through increased cell-cycle progression and reduced cell death." (PMID 36046049, 2022). "Thus, it will be crucial to evaluate different approaches to inhibit STAT3 signaling in the tumor cells and in the tumor microenvironment alone or in combination with immune therapy." (PMID 35267462, 2022). "There are seven proteins in the STAT family, among which STAT1 and STAT2 play an important role in anti-tumor immune response, STAT3 and STAT5 are related to tumorigenesis, especially STAT3 is closely related to cancer cell survival, immunosuppression, and persistent inflammation." (PMID 36686745, 2022). "Additionally, we report the small molecule inhibitor AC-4-130 inhibits both STAT5 and STAT3 activation in our experimental setting, significantly inhibiting tumor development in vivo and highlighting the added benefit of a dual STAT3/5 inhibition." (PMID 36045346, 2022). "Recently, our laboratory and others showed that either Olaparib or PARP1 gene silencing activated STAT3 by increasing STAT3 phosphorylation through dePARylation in cancer cells and immune cells, partially counteracting the tumor cell-killing efficacy of Olaparib." (PMID 36324587, 2022). "STAT3 expression is also essential for primary 4T1 tumor growth and metastasis." (PMID 35076584, 2022). "Thus, JAK2/STAT3 pathway is a well-known therapeutic target for curcumin inhibiting tumor initiation." (PMID 35883653, 2022). "(-)-Antofine at a dose of 5 mg/kg reduced tumor growth and decreased Met-mediated STAT3." (PMID 35805049, 2022). "TAMs also secrete IL-6 and IL-10, which activate the STAT3 pathway and promote tumor proliferation." (PMID 36532066, 2022). "The anti-cancer and anti-inflammatory effects of UA are mediated via various signaling cascades, including the signal transducer and activator of transcription 3 (STAT3) and NF-κB signaling pathways and the Akt/p70S6K signaling pathways to suppress tumor growth, survival and metastases." (PMID 35204066, 2022). "This is because the IL-6/STAT3 pathway favors the immunosuppressive cells and dysregulates the T cell subsets, such as myeloid-derived suppressor cells (MDSCs) and T regulatory cells, leading to tumor progression." (PMID 35444660, 2022). "IL6 promotes tumor cell proliferation, survival, and metastasis through activation of Stat3." (PMID 35200587, 2022). "Additionally, baicalin also showed the capability of inhibiting the upregulation of PD-L1 induced by the IFN-γ via mediating the activation of STAT3, thus enhancing the elimination of tumor cells induced by CTLs." (PMID 36615387, 2022). "During hepatocellular carcinogenesis, IL-6 trans-signaling pathway, rather than the IL-6 classic signaling contributes to the development of tumors by enhancing tumor proliferation through STAT3 and β-catenin activation and stimulating endothelial cell proliferation to promote tumor angiogenesis." (PMID 36276076, 2022). "Indeed, our results show that STAT3 activation mediated by elevated IL-6 plasma concentration and oxidative damage in skeletal muscle plays a key role in tumor-induced muscle atrophy." (PMID 35847939, 2022). "Subsequently, these extracellular signals are transduced into the nucleus by STAT3 protein with a cascade of recruitment, phosphorylation, dimerization and translocation, transcriptionally modifying the survival, proliferation, and metastasis of tumor cells." (PMID 36080223, 2022). "Tumor cells contain a large number of active phosphorylated STAT3." (PMID 35744840, 2022). "Gene set enrichment analysis (GSEA) illustrated that the common enriched Hallmark sets between cells and tumours were associated with cytokine or chemokine‐related signalling pathways (such as NF‐κB and IL6/JAK/STAT3 pathway), apoptosis, and epithelial mesenchymal transition." (PMID 36116131, 2022). "It was known that p-STAT3 (Tyr705) in the nucleus can promote tumor growth." (PMID 36443287, 2022).
tumor (continued). "A large number of previous studies have confirmed the role of STAT3 in tumours." (PMID 36225565, 2022). "Cytokines produced by immune T cells can activate STAT3 in tumor tissues and affect tumorigenesis." (PMID 36686745, 2022). "Finally, STAT3 inhibitor treatment significantly prevents in vivo tumor formation in genetically engineered Shh MB mice." (PMID 34482626, 2022). "In addition to the tumor-promoting effects described previously, plenty of evidence indicates that STAT3 can be used as a tumor suppressor in various tumors under certain conditions." (PMID 36557902, 2022). "Therefore, targeting STAT3 can inadvertently lead to the downregulation of STAT1 and the associated advantages to tumor cells." (PMID 35053592, 2022). "Additionally, IL-6, a chronic inflammatory protein that induces CRP expression, was also reported to have a potential immune suppressive function and promote tumor progression by inducing tumor cell expression of STAT3 and its downstream target genes." (PMID 35185894, 2022). "In this schema, upon inhibition of Stat3 activity, tumor cells, having high E2F levels, may succumb to apoptosis." (PMID 35411090, 2022). "The highly expressed IL-6 can promote inflammation and tumor cell immunosuppression, and possibly aggravate tumor cell growth and metastasis by IL-6/Signal Transducer And Activator Of Transcription 3 (STAT3) mediated inhibition of DC and lead to the dysfunction of the immune system." (PMID 36004920, 2022). "Existing studies have confirmed that the STAT3-mediated inhibitory tumor immune response pathway has an antagonistic effect on the STAT1-driven antitumor immune response, which may lead to the loss of IFNγ/JAK/STAT1 pathway function." (PMID 36185620, 2022). "STAT3-dependent feedforward signaling loops are formed, which further fuel tumor progression." (PMID 35836213, 2022). "To determine whether these signaling pathways are blocked in tumor vessels in vivo by rNDV-VEGF-Trap, we employed Western blot for detection of ERK (P-ERK), AKT (P-AKT) and STAT3 (P-STAT3) in the tumor tissue of mice." (PMID 35381011, 2022). "STAT3 activation reversed miR-577-mediated anti-tumor roles." (PMID 35475457, 2022). "Downregulation of MMP9, EGFR, VEGFR and STAT3 in HepG2 cancer cells could appear to play a role in tumor invasion and angiogenesis and to mediate the tumor microenvironment." (PMID 36284117, 2022). "In the tumor microenvironment, the constitutive STAT3 activation could be prolonged by STAT3-mediated factors, including vascular endothelial growth factor (VEGF) and interleukin-10 (IL-10), which generate immunosuppression in innate and adaptive immunity." (PMID 35936759, 2022). "Increase in VEGFA levels mediated by STAT3-signaling plays a critical role in tumor angiogenesis." (PMID 36010595, 2022). "Stat3 antisense gene therapy induced tumor cell apoptosis by targeting Stat3." (PMID 34875483, 2022). "We identify the existence of a molecular mechanism shielding the tumor from immune attack regulated by the IL-6/STAT3/SMG1 axis that prevents antitumor immune responses: a new immunoediting process to silence potent neoantigens by immune intrinsic pathways that affect the activity of NMD." (PMID 36443756, 2022). "Indeed, IL-17 induces IL-6 production that in turn activates STAT3-dependant pathways, thereby promoting the proliferation of HepG2 cells in vitro and tumor growth after orthotopic liver transplantation." (PMID 35342340, 2022). "Through gene enrichment analyses, functional assays, and biochemical experiments, a RNF7-SOCS1/JAK/STAT3 pathway was uncovered, and its functional relevance in regulating cell viability, apoptosis, and glycolysis in vitro and tumor growth in vivo was demonstrated." (PMID 35562668, 2022). "Many lncRNAs have been reported to promote tumor growth through STAT3 in NSCLC." (PMID 35740511, 2022). "Lastly, we found that TAb2 tumor expressed a higher level of p-STAT3." (PMID 35366939, 2022).
tumor (continued). "Aspirin can reduce vessel formation and triggers apoptosis by reversing the balance of pro- and anti-angiogenetic effects in the tumor microenvironment and modulating both the nuclear factor kappa B (NF-κB) and the signal transducer and activator of transcription 3 (STAT3) pathways." (PMID 35267516, 2022). "Consequently, hindering STAT3 phosphorylation resulted in tumor inhibition in TNBC with high ENSA expression." (PMID 35145111, 2022). "STAT3 inhibitors not only suppress tumour cells but also enhance immune cell responses." (PMID 36678509, 2022). "In addition, inhibition of IL-6 expression in CAFs or JAK2/STAT3 pathway in GC cells can impair the peritoneal metastasis of tumor induced by CAFs in vivo." (PMID 36591515, 2022). "The findings of the current study showed that FTO inhibited expression of APOE through IGF2BP2-mediated m6A modification and may inhibit glycolytic metabolism in PTC by modulating IL-6/JAK2/STAT3 signaling pathway, thus abrogating tumor growth." (PMID 35090515, 2022). "Persistent activation of STAT3 could be crucial for tumor progression and epithelium-mesenchyme transition, a process also regulated by E2 in GBMs." (PMID 35197928, 2022). "IL-6 stimulates the invasion and growth of GBM tumor cells by binding to heterogeneous membrane receptor complexes (formed by IL-6r and glycoprotein 130) and initiating typical IL-6 signal transduction, such as STAT3." (PMID 35572545, 2022). "Inhibition of the IL‐6/JAK/STAT3 pathway suppressed tumor growth in the N‐inv model and could represent a candidate target for the treatment of PDAC." (PMID 35578571, 2022). "The activation of REG3A will enhance the JAK2/STAT3 pathway and form a positive feedback loop of REG3A-JAK2/STAT3, thereby amplifying the carcinogenic effect of IL-6/JAK2/STAT3, and ultimately leads to excessive PC cell proliferation in vitro and in vivo and tumor formation." (PMID 36591515, 2022). "This drug has recently been described as a potent Stat3 inhibitor capable of suppressing Stat3 phosphorylation at Tyr705 and transcript activity; moreover, a correlation between Stat3 and the accumulation of myeloid-derived suppressor cells (MDSCs) in tumor-bearing mice has been demonstrated." (PMID 35138629, 2022). "In addition, the limiting dilution assay revealed that STAT3 knockdown led to a reduced number of tumor-initiating cells." (PMID 35562901, 2022). "ROS could regulate a variety of signaling pathways, including PI3K/AKT, hypoxia-inducible factor-1α (HIF-1α), c-myc, NF-κB, and STAT3, and other molecules, thus linking to growth, metastasis, angiogenesis and chemoresistance of tumor." (PMID 35646942, 2022). "Furthermore, reduced FTO in combination with m6A modification of APOE can modulate the IL-6/JAK2/STAT3 signaling pathway to promote tumor glycolysis, thereby aggravating the progression of PTC." (PMID 36506554, 2022). "Therefore, the JAK/STAT3 pathway in tumor cells and various stromal cells in their microenvironment is often considered as an effective target for tumor therapy." (PMID 35559037, 2022). "In addition to promoting carcinogenesis, STAT3 activation can block STAT1-mediated tumor suppression." (PMID 36439472, 2022). "Numerous studies show that, within the tumor microenvironment, STAT3 signaling induces pro-carcinogenic cytokines (such as IL-6, IL-10, and IL-23) and inhibits anti-carcinogenic cytokines (e.g., IL-12), thereby promoting tumor immune evasion and cancer progression." (PMID 36557902, 2022). "CAF in tumor microenvironment promotes GC progression through IL-6/JAK2/STAT3 signal transduction." (PMID 36591515, 2022). "Previous studies have indicated that G‐CSF or GM‐CSFs can affect differentiation of bone marrow cells and increase the ratio of tumor‐associated immunosuppressive cells through triggering JAK protein kinases phosphorylation and subsequent activation of STAT3/STAT5 transcription factors." (PMID 35612789, 2022).